Y_RNA (Y RNA )
Gene: Miscellaneous RNA gene on chromosome 6 (79,301,963 to 79,302,066, reverse strand). Ensembl gene ENSG00000201464.
Homologues: Orthologues: chimpanzee Y_RNA (100% identical). Paralogues in human: Y_RNA (81% identical), Y_RNA (79% identical), Y_RNA (78% identical), RNY1 (77% identical), RNY1P5 (77% identical), Y_RNA (77% identical), Y_RNA (76% identical), RNY1P2 (75% identical), RNY1P7 (75% identical), Y_RNA (75% identical), Y_RNA (74% identical), RNY1P11 (73% identical), and 87 more.